KRAS (KRas proto-oncogene, GTPase)
Diseases named in the same sentence as KRAS in open-access papers (continued):
Sharing a sentence is not in itself a finding about the gene and the disease.
lung adenocarcinoma (continued). "To analyze how oncogenic KRAS regulates ACAA1 expression and the related upstream signaling pathway, we used lung adenocarcinoma cell line H1944, which harbors KRASG13D mutation." (PMID 33194642, 2020). "The Kirsten rat sarcoma (KRAS) and epidermal growth factor receptor (EGFR) mutations play an important role in the pathogenesis of most lung adenocarcinomas and are, with rare exceptions, mutually exclusive, and vary by geography." (PMID 33194700, 2020). "This can be explained by the fact that STK11 deletion in KRAS-driven lung adenocarcinoma promotes the accumulation of neutrophils with T-cell suppressive function, as observed in mouse models." (PMID 33114576, 2020). "By tracking the evolution of lung adenocarcinomas, most BRAF, EGFR, and KRAS activating mutations are trunk drivers." (PMID 32333643, 2020). "Somatic activating mutations of the KRAS gene are the most observed in NSCLC, especially in lung adenocarcinoma (about 20–30%), and less frequently in in squamous cell carcinoma (about 5%)." (PMID 32365882, 2020). "PKCλ also controls the Notch signaling pathway, a key driver of stemness in KRAS-mediated lung adenocarcinoma and in glioblastoma." (PMID 32658903, 2020). "An analysis of the TCGA’s KRAS mutant lung adenocarcinoma cohort defined a 4-gene signature of mutant tumors (overexpressing FOXRED2, TOP1, PEX3, and ABL2)." (PMID 32725342, 2020). "Other clinical trials for KRAS‐mutant lung adenocarcinoma patients exploring the benefits of ICIs are still ongoing (NCT03777124, etc)." (PMID 33022831, 2020). "The emblematic KRAS mutant cancers are pancreatic, colorectal, lung adenocarcinomas and urogenital cancers." (PMID 32725342, 2020). "Clinicopathological parameters according to the mutant ctDNA in EGFR or KRAS-mutant lung adenocarcinoma (n = 21)." (PMID 32196518, 2020). "An earlier report suggests that PKCλ activates NOTCH3 expression via ELF3 phosphorylation, and this axis maintains the highly tumorigenic TIC phenotype in KRAS-mediated lung adenocarcinoma." (PMID 32658903, 2020). "Our study revealed that concurrent genomic alterations can further stratify KRAS‐mutant lung adenocarcinoma patients into various subgroups with distinctive therapeutic responses and differential survival outcomes." (PMID 31709742, 2020). "A phase I/IIa trial is designed to study the combination of rigosertib plus nivolumab (an immune checkpoint inhibitor) in metastatic KRAS+ lung adenocarcinoma adult patients who have progressed on standard first-line treatment (NCT04263090)." (PMID 32560574, 2020). "We infer that FGL2 affect KRAS by influencing immune status in tumor environment of lung adenocarcinoma." (PMID 32206449, 2020). "All patients were EGFR/KRAS wild-type, 14 cases of which were lung adenocarcinoma and 20 cases lung squamous cell carcinoma." (PMID 32775040, 2020). "Intrinsic mutations on the Kristen Rat Sarcoma Viral Oncogene homolog (KRAS) are important alteration that occurs in 25% of lung adenocarcinoma." (PMID 32111002, 2020). "Patients with KRAS mutant lung adenocarcinomas showed significant treatment benefits, with 60% of patients showing tumor reductions—of which, 30% were partial responses." (PMID 32560574, 2020). "In lung adenocarcinoma (LUAD), the most frequent oncogene driver mutation is Kirsten Rat Sarcoma (KRAS)." (PMID 33072585, 2020).
lung adenocarcinoma (continued). "Elevated in KRAS mutant lung adenocarcinoma with low expression of TTF-1; Seliencing REG4 reduced cancer cell proliferation and tumorigenesis via blocking G2/M transition." (PMID 33489872, 2020). "REG4 promotes the progression in KRAS mutant lung adenocarcinoma cells progression and can be used as a novel biomarker in lung adenocarcinoma subtype." (PMID 33489872, 2020). "The results demonstrated a high agreement between meth-HOXA9 and mut-KRAS in patients with advanced lung adenocarcinoma." (PMID 33322500, 2020). "Intriguingly, it has been seen that driver fusions in lung adenocarcinomas co-occur with SETD2 mutations (16% of cases) in contrast with lung adenocarcinomas with EGFR, KRAS, BRAF and MET mutations, where the frequency of SETD2 mutations is only 2%." (PMID 32516941, 2020). "A former study showed that oncogenic KRAS induces fatty acid synthase (FASN) to enhance lipogenesis with a specific lipid signature in lung adenocarcinoma." (PMID 33194642, 2020). "The first-line Bevacizumad and platinum based chemotherapy for patients with advanced lung adenocarcinoma, the patients with KRASG12D mutation had significantly poorPFS and OS than patients with wild-type KRAS or other KRAS mutations." (PMID 32244355, 2020). "RAS and RAF mutations are implicated in a great portion of malignancies: BRAF V600 mutation is found in 40–60% of melanomas and 10–12% of metastatic colorectal cancer (mCRC), KRAS or NRAS in 55% of mCRC, and KRAS in 20–30% of lung adenocarcinoma." (PMID 33109256, 2020). "Meth-HOXA9 and mut-KRAS were measured by ddPCR in DNA from tumor and plasma from 34 patients with incurable lung adenocarcinoma." (PMID 33322500, 2020). "KRAS p.G12C mutations were most predominant in NSCLC which was comprised about 11–16% of lung adenocarcinomas (p.G12C accounts for 45–50% of mutant KRAS)." (PMID 32117436, 2020). "In this study, we explored the potential synergistic effect of the combination of Id1 inhibition and pharmacological PD-L1 blockade in three different syngeneic murine KRAS-mutant lung adenocarcinoma models." (PMID 33126649, 2020). "In contrast, IKKα activity promotes human lung adenocarcinoma in Kirsten Rat Sarcoma (KRAS)-mutant cells and in response to chemical carcinogens." (PMID 35582445, 2020). "The dominant mutations found frequently in lung adenocarcinomas, such as EGFR, ALK and KRAS mutations, are uncommon in SQCC." (PMID 31829519, 2020). "Both KRAS and EGFR mutations are identified almost exclusively in lung adenocarcinomas, similarly to rearrangements involving ALK and ROS1, which were described in 2007." (PMID 32604993, 2020). "Despite this, a recent report has suggested that patients with KRAS-mutant lung adenocarcinoma have a poorer outcome on pemetrexed-based first-line chemotherapy." (PMID 31739412, 2019). "The KRAS oncoprotein, a critical driver in 33% of lung adenocarcinoma (LUAD), has remained an elusive clinical target due to its perceived undruggable nature." (PMID 31519898, 2019). "KRAS is frequently mutated in pancreatic and colorectal cancer (CRC), and in lung adenocarcinoma (LADC)." (PMID 31600989, 2019).
lung adenocarcinoma (continued). "Mutations to KRAS are recurrent in lung adenocarcinomas (LUAD) and are daunting to treat due to the difficulties in KRAS oncoprotein inhibition." (PMID 31036704, 2019). "Subset analysis showed that these correlations were strongest in KRAS wild‐type lung adenocarcinomas." (PMID 30972766, 2019). "Recently, it was reported that KRAS mutation induced upregulation of PD-L1, through p-ERK, mediated immune escape in lung adenocarcinoma, and induces the apoptosis of CD3-positive T cells, which were reversed by anti-PD-L1 or ERK inhibition." (PMID 30824880, 2019). "Lung adenocarcinoma can be classified according to the presence of major driver mutations in EGFR, KRAS, ALK, and BRAF, which confer clinical benefits to the subset of patients harboring them." (PMID 31083279, 2019). "1,760 lung adenocarcinoma patient blood samples were tested for analyzing mutations in EGFR, KRAS, NRAS, PIK3CA, HER2, BRAF and MET in cfDNA." (PMID 31749831, 2019). "Following the identification of KRAS and BRAF mutations, epidermal growth factor receptor (EGFR) mutations were discovered in patients with lung adenocarcinoma and were associated with response to EGFR inhibitors." (PMID 31092229, 2019). "For this reason, we modelled this in a well-characterised genetic mouse model of lung adenocarcinoma development driven by oncogenic KRAS." (PMID 30760495, 2019). "Kirsten rat sarcoma viral oncogene (KRAS) and epidermal growth factor receptor (EGFR) are the most frequent and well-known mutated oncogenes in adenocarcinoma of the lung." (PMID 31783917, 2019). "This work argued that genomic alterations co-occurring with mutant KRAS stratify lung adenocarcinomas and define pathobiological properties and therapeutic vulnerabilities." (PMID 31612108, 2019). "Next we attempted to extend and validate these findings in human H1792 KRAS-mutant lung adenocarcinoma CSCs/spheres." (PMID 31001473, 2019). "Administration of SMAP therapy to activate PP2A in KRAS-driven lung adenocarcinoma mouse xenografts resulted in the inhibition of tumour growth, decreased phosphorylation of ERK and induction of apoptosis of cancer cells when compared to vehicle controls." (PMID 31623614, 2019). "Mutations in EGFR (epidermal growth factor receptor 1) and KRAS (Kirsten rat sarcoma viral oncogene homolog GTPase) and ALK (anaplastic lymphoma kinase) rearrangements are mostly found in lung adenocarcinoma, accounting for 30–40% of NSCLCs." (PMID 31795465, 2019). "Here, we screened 230 Chinese patient samples of lung SCC and reported the rarity of two most ubiquitous mutations in KRAS and EGFR seen in lung adenocarcinoma, while PIK3CA mutations were relatively high when compared with lung adenocarcinoma." (PMID 31749831, 2019). "KRAS mutation is one of the most frequent mutations in NSCLC, at least in Caucasian populations, with reported frequencies reaching up to 30% of lung adenocarcinomas, while its prevalence in Asian populations is approximately 10%." (PMID 30744664, 2019). "Blockade of PD-1/PD-L1 signaling would thus be a promising therapeutic strategy for KRAS-mutant lung adenocarcinoma." (PMID 31775797, 2019). "Mutations in KRAS and EGFR are common driver mutations in lung adenocarcinomas, with ~25% and ~15% incidence, respectively." (PMID 31581742, 2019). "Here we report an adaptation of this platform to identify genetic drivers that synergize with mutant KRAS to advance tumor progression and metastasis in lung adenocarcinoma." (PMID 30013058, 2018).
lung adenocarcinoma (continued). "In fact, there is evidence from transgenic mouse models and cancer cell lines that simultaneous activating mutations in KRAS and EGFR lead to cell death in lung adenocarcinoma." (PMID 29854275, 2018). "Initial studies in animal models provided evidence NFkB activity is required for KRAS-initiated lung adenocarcinoma development because it supports cell survival." (PMID 30060526, 2018). "Several parenchymal and stromal targets detected by TCSG in the tumor xenograft were selected for IHC-based validation on human lung adenocarcinoma tissue known to contain an oncogenic KRas mutant." (PMID 29899869, 2018). "As far as we know, this study is the first study to compare the efficacy of pemetrexed-based chemotherapy between HER2-mutant and groups of EGFR-mutant, ALK/ROS1-rearranged and KRAS-mutant lung adenocarcinoma." (PMID 29587667, 2018). "Both studies are based on surgically resected lung cancer samples of East Asian populations, in which the frequencies of KRAS and EGFR mutations are reported to be 8–10% and 40–55%, respectively, in lung adenocarcinomas." (PMID 30445777, 2018). "Pancreas adenocarcinoma (somatic mutation frequency 90.6%), colorectal adenocarcinoma (42.5%), and lung adenocarcinoma (32.6%) are the top three most KRAS mutant primary cancer types." (PMID 30406144, 2018). "It is important to point out that MAPK activation score is higher among KRAS mutant lung adenocarcinomas, but it is present also among KRAS WT adenocarcinomas." (PMID 30060526, 2018). "The lung adenocarcinoma dataset SRA ERP001058 contains 41 tumors with known targetable or oncogenic mutations in 6 genes: EGFR, KRAS, NRAS, MET, BRAF and CTNNB1." (PMID 30255803, 2018). "Another molecular event cooperating with KRAS in driving lung adenocarcinoma development is represented by MYC activation." (PMID 30060526, 2018). "This review summarizes the state of knowledge of tumorigenesis and progression of early lung adenocarcinoma, with a special focus on its clinicopathological characteristics and their associations with driver mutations (EGFR, KRAS, and BRAF)." (PMID 29690599, 2018). "This review presents the current knowledge of the processes of tumorigenesis and progression in early lung adenocarcinoma, with a focus on its clinicopathological characteristics and their associations with driver mutations (EGFR, KRAS, and BRAF)." (PMID 29690599, 2018). "Because both A549 and Panc-1 are KRAS mutant cancer cell lines, we next checked the effects of COPS5 knock-down in H1650 or H2228 lung adenocarcinoma cell lines, which has an EGFR mutation or EML4-ALK fusion, respectively." (PMID 29755680, 2018). "EGFR, KRAS, HER2, BRAF, and PIK3CA mutations are these important genetic alterations in the targeted therapies of lung adenocarcinoma." (PMID 29518290, 2018). "Inhibition on NOTCH signaling markedly reduced KRAS-induced adenocarcinoma formation, while NOTCH activation in bronchiolar cells rnhanced KRAS-induced lung adenocarcinomas." (PMID 30060526, 2018). "We also identified CD4+ T cell responses to the recurrent KRAS G12V and Her-ITD mutations in 2 different patients with lung adenocarcinoma." (PMID 30400835, 2018). "As above repeatedly mentioned, about 20% of KRAS mutant lung adenocarcinomas display KEAP1 loss, often associated with KRAS mutations." (PMID 30060526, 2018).
lung adenocarcinoma (continued). "Genes found up-regulated in KRAS models were next triangulated with human copy number amplifications documented by TCGA (1.5-fold somatic amplification across ≥5% of 154 analyzed lung adenocarcinoma specimens)." (PMID 30013058, 2018). "The CD44 antigen (CD44), depicted in the tumor invasion network was selected for orthogonal cross-validation because of its well-described role in tumorigenesis and invasion of lung adenocarcinoma driven by oncogenic KRas mutants." (PMID 29899869, 2018). "Recent studies have addressed a role for IKKα in cooperation with KRAS in the induction of lung adenocarcinomas." (PMID 30060526, 2018). "Despite major improvements made with early detection, and increased knowledge and identification of actionable tumor biomarkers, KRAS-driven lung adenocarcinoma still represents a commonly diagnosed form of NSCLC for which there are no targeted agents." (PMID 30013058, 2018). "Synthetic lethality results when mutant KRAS and EGFR proteins are co-expressed in human lung adenocarcinoma (LUAD) cells, revealing the biological basis for mutual exclusivity of KRAS and EGFR mutations." (PMID 30475204, 2018). "The study of animal models of lung adenocarcinoma helped to define the role of many other genes that cooperates with KRAS in inducing tumor development." (PMID 30060526, 2018). "We identified three genes (GATAD2B, ACVR1B, and ZC3H11A) whose overexpression significantly correlates with mutant KRAS lung adenocarcinoma vs wild-type KRAS status in patients." (PMID 30013058, 2018). "Recently, Davar reported a patient with advanced, heavily pretreated KRAS-mutant lung adenocarcinoma who developed an excellent response after a single-dose of anti-PD-1 antibody (nivolumab)." (PMID 28451792, 2017). "In the KRAS G12D substitution induced lung adenocarcinoma mouse model, WNT signaling enhances proliferation and EMT." (PMID 28870231, 2017). "A total of 72 surgically resected lung adenocarcinoma specimens (19 EGFR-mutated, 17 KRAS-mutated, 16 ALK-rearranged, and 20 triple negative cancers) were screened for 23 microRNAs using quantitative real-time reverse transcriptase polymerase chain reaction." (PMID 28035073, 2017). "The initial pathologic diagnosis was lung adenocarcinoma stage IIIa (pT3 pN1 Mx), KRAS wild-type, harboring EGFR exon 19 deletion and EML4-ALK rearrangement." (PMID 28938691, 2017). "The frequencies of driver genetic alterations in Caucasians were determined in TCGA study, whereas lung adenocarcinoma in Asians is characterized by a high frequency of EGFR mutations (approximately 50%) and low frequency of KRAS mutations (approximately 10%)." (PMID 28894699, 2017). "Lung adenocarcinoma has distinctive clinicopathological features that are related to specific genetic alterations, including EGFR and KRAS mutations and ALK rearrangement." (PMID 28035073, 2017). "We investigated PD-L1 changes in response to MEK and AKT inhibitors in KRAS mutant lung adenocarcinoma (adeno-NSCLC)." (PMID 28982179, 2017). "We went on to derive cell lines from eight patients with lung adenocarcinoma-induced MPE that were initially tested KRAS wild-type." (PMID 28508873, 2017). "In this study, we investigated the correlation between PD-L1 expression and KRAS mutation and the functional significance of PD-1/PD-L1 blockade in KRAS-mutant lung adenocarcinoma." (PMID 28451792, 2017). "At present, therapy with PD-L1 axis blockade appears to be at least as effective in KRAS-mutant lung adenocarcinomas, compared to wild-type." (PMID 28716137, 2017). "Here, we demonstrate lineage switching of KRAS+ lung adenocarcinomas (ADC) to squamous cell carcinoma (SCC) through deletion of Lkb1 (Stk11) in autochthonous and transplant models." (PMID 28387316, 2017).